INHBA (inhibin subunit beta A)
Diseases named in the same sentence as INHBA in open-access papers (continued):
Sharing a sentence is not in itself a finding about the gene and the disease.
cancer (continued). "Inhibin subunit beta A (INHBA) is a member of the transforming growth factor-beta (TGF-β) superfamily that plays a fundamental role in various cancers." (PMID 37528145, 2023). "Overexpression of INHBA has been reported in several cancers, such as those of the colon and stomach." (PMID 36348017, 2023). "INHBA plays an important role in the progression of various (including esophageal, breast, lung, and gastric) cancers." (PMID 37940978, 2023). "INHBA, a member of the TGF-β superfamily, has been reported to be overexpressed in multiple types of cancers, including ESCC, and associated with poor prognosis." (PMID 37644505, 2023). "INHBA is a member of the TGF-β protein superfamily, and has been associated with the occurrence of some cancers." (PMID 37446311, 2023). "In this study, we first assessed the expression profile of INHBA in cancers using Oncomine and TIMER2.0 databases." (PMID 36304286, 2022). "The mRNA expression of INHBA in different types of human cancer was analyzed using the Oncomine database." (PMID 36304286, 2022). "Through the cell experiment results, we found that NFKBIA played a protective role, while INHBA played the pro-cancer role." (PMID 35999846, 2022). "Note that BMP15 and INHBA cancers originate in distinct cell types (squamous cells vs epithelial cells, respectively), limiting the relevance of these mutations to understand heterodimerization." (PMID 36214621, 2022). "Over the last couple of decades, the role of INHBA in various malignant tumors has been gradually explored." (PMID 35236827, 2022). "In other cancer types, aberrant increases in INHBA expression have been reported in both the epithelial and CAF components, involving autocrine and paracrine functions." (PMID 34642171, 2022). "We first analyzed the correlation between INHBA (inhibin subunit βA) expression and the prevalence of cancer cachexia in 18 types of cancer using RNA-Seq data from The Cancer Genome Atlas (TCGA)." (PMID 35102236, 2022). "Collectively, our data and previous studies support the notion that INHBA upregulation in cancer promotes EMT and cell invasion by activating TGF-β pathway." (PMID 34346300, 2021). "For example, cancer cells were sensitive to Tyrothricin with the increased expression of INHBA genes, while they were insensitive to Zoledronate." (PMID 34692520, 2021). "INHBA encodes a member of the TGF-beta superfamily of proteins, which has been found to be associated with various types of human cancers." (PMID 34968391, 2021). "LIF can promote cancer cell progression, including migration and invasion, through INHBA in OSCC cells." (PMID 31973037, 2020). "The function of the identified neighbor genes of INHBA was involved in the activing binding, protein complex form, regulation of protein and several cancer processes." (PMID 31586103, 2019). "Activin A, a member of the TGFβ superfamily comprising two INHBA subunits, has been shown to play context-depended roles in cancer progression." (PMID 30805303, 2019). "In contrast, levels of expression of inhibin beta A (INHBA) were significantly higher in cancer tissue than in adjacent normal mucosa, and it is regarded as an independent prognostic factor in gastric cancer." (PMID 25928635, 2015). "The prominent presence in the signature of INHBA in all cancers strongly suggests a biological mechanism centered on activin A induced TGF-β signaling, because activin A is a member of the TGF-β superfamily consisting of an INHBA homodimer." (PMID 21047417, 2010). "Moreover, these two SBS subtypes differed in somatic mutations in several cancer driver genes, including higher mutation frequency of ERBB2, GATA3 and FGFR4, and lower frequency of DMD, INHBA, OGDHL, PLEKHG5 and RYR2 in subtype 3 than in subtype 1 (P < 0.05)." (PMID 40858906, 2025). "Furthermore, INHBA has been identified as a novel regulator of cellular senescence and immune evasion in cancer, highlighting its potential broader role in aging pathologies." (PMID 41463387, 2025).
cancer (continued). "The INHBA gene is another gene observed in cancer cells resistant to paclitaxel." (PMID 39003454, 2024). "INHBA affects cancer progression by regulating a plethora of oncogenic hallmarks." (PMID 38329386, 2024). "Additionally, uncertainty regarding the origin of INHBA overexpression in solid tumors has arisen due to the use of poorly-validated INHBA antibodies in the analysis of cancer tissues." (PMID 38360876, 2024). "INHBA mRNA is upregulated in multiple cancer types in comparison to normal tissues." (PMID 38360876, 2024). "Unlike αSMA(+) CAFs, INHBA(+) CAFs were enriched in HGSOC metastases and their proportion correlated with poor patient survival, suggesting that INHBA(+) CAFs might be active participants in cancer progression." (PMID 38360876, 2024). "Although the roles of INHBA in cancer are controversial, the majority favor its oncogenic effects." (PMID 37644505, 2023). "INHBA is a protein-coding gene, belonging to transforming growth factor β superfamily, which may play a considerable role in the progression of various cancers." (PMID 36984496, 2023). "However, the UALCAN cancer database showed that INHBA protein expression was significantly higher in the stage I group compared with the stage II and III groups." (PMID 36304286, 2022). "Previous studies revealed that the overexpression of INHBA may be affected by promoter methylation in cancer." (PMID 35216189, 2022). "Future studies could explore the therapeutic effect of metformin in other malignant tumors with high INHBA expression and the detailed regulation mechanism of metformin on INHBA expression." (PMID 35236827, 2022). "High INHBA expression levels may facilitate activin A, the formation of INHBA homodimers, leading to activation of activin receptors in cancer." (PMID 35216189, 2022). "Many studies have proved that INHBA serves important roles in various cancer progressions." (PMID 34889158, 2021). "Furthermore, GEO dataset analysis revealed that mDia2/DIAPH3 and INHBA were both overexpressed in the stromal compartment of several cancers in comparison with the respective normal tissue and also in breast CAFs compared to normal breast fibroblasts." (PMID 32150356, 2020). "We demonstrated a novel mechanism (INHBA regulation) by which LIF influences cancer progression." (PMID 31973037, 2020). "Box plot showing INHBA mRNA levels in, respectively, the Peng Head-Neck, Sengupta Head-Neck, Ginos Head-Neck, Ye Head-Neck and Pyeon Multi-cancer Head-Neck datasets, meanwhile, the fold change differences all were over 2 means that INHBA expression were significantly higher in HNSCC tissues." (PMID 31586103, 2019). "In summary, our results showed that blocking INHBA in cancer cells may be a potential therapeutic strategy to inhibit SOC progression." (PMID 31827640, 2019). "Therefore, the purposes of this study were to evaluate the expression of INHBA in OC tissues and to characterize the pivotal role of cancer cell-derived INHBA in stromal fibroblast activation and SOC progression." (PMID 31827640, 2019). "Therefore, the biological interaction network of INHBA alterations is engaged with the activing binding, protein complex form, regulation of protein and several cancer processes." (PMID 31586103, 2019). "The molecular mechanisms by which INHBA affects cancer progression remain elusive." (PMID 31827640, 2019). "In addition, abnormal overexpression of INHBA was detected in various malignant tumors, including esophageal cancer, prostate cancer, and ovarian cancer." (PMID 31586103, 2019). "In addition, IKZF1 encodes a TF regulating lymphocyte differentiation, and INHBA, which belongs to the TGF-β superfamily, is associated with several cancers." (PMID 27829444, 2016). "The response of CPB cells to INHBA overexpression indicated that premalignant cells or cells at an early stage of EAC progression reduce their capability for cell survival or self-renewal while cancer cell lines evade a Activin A-mediated response." (PMID 26447543, 2015).
cancer (continued). "INHBA overexpression may be affected by promoter methylation in cancer cells." (PMID 35216189, 2022). "Collectively, INHBA may play an important role in regulating the CAF phenotype in cancers." (PMID 35216189, 2022). "This study could help us better understand INHBA-mediated interaction between cancer cells and stromal fibroblasts, providing evidence to support that targeting INHBA in cancer cells to inactivate stromal fibroblasts could be a promising SOC therapeutic strategy." (PMID 31827640, 2019). "Cytoskeletal regulators (MYL9, TAGLN) and transcription factors (SNAI2) promote EMT and cancer stemness, while PMEPA1, IL6, IL8, IGFBP3, INHBA, and VEGFA contribute to proliferation, angiogenesis, and immune modulation." (PMID 41009714, 2025). "Key oncogenes, including SERPINE1, MMP13, INHBA, and SPARC, emerged as central to these effects, consistent with their reported contributions to cancer progression across various malignancies." (PMID 40361356, 2025). "Chen and his coworkers (2019) observed that the INHBA gene induces the TGF-β signaling pathway, promoting cancer cell motility, invasion, migration, and consequently cancer cell resistance." (PMID 39003454, 2024). "Particularly, the expression of INHBA, HSP90AA1 and EIF2AK2 in ESCC cancer tissues was significantly higher than that in normal tissues, while the level of LRRK2 and HSPB8 in ESCC tissues was remarkably lower as compared to the normal tissues." (PMID 39006030, 2024). "INHBA, as a member of the TGF-β superfamily, plays an important role in the progression of various cancers through regulating TGF-β signaling pathway." (PMID 37940978, 2023). "INHBA has been involved in regulating TGF-β signaling pathway to promote the proliferation, migration, and invasion in cancer cells." (PMID 37940978, 2023). "Pan-cancer Kaplan-Meier survival analysis on 21 human cancer types revealed significant prognostic values for INHBA and NEK2 in at least 16 cancer types." (PMID 37667354, 2023). "WGCNA revealed dMMR/MSI-correlated gene modules, including INHBA and RPL22L1, which were upregulated; conversely, HMGCS2 was downregulated in MSI cancer." (PMID 35909892, 2022). "Nevertheless, INHBA, as a member of the TGF-β family, has pro- or antitumorigenic effects in diverse cancers." (PMID 36304286, 2022). "In this study, our results confirmed that circTHBS1 and INHBA share the same MRE in miR-204-5p, a downregulated miRNA with cancer suppressing function that was clearly validated in our previous study, therefore forming a circTHBS1/miR-204-5p/INHBA axis." (PMID 35338119, 2022). "Our GO enrichment revealed that RPL22L1, INHBA, and CAPZA1 had a significantly higher expression levels in MSI than in MSS, and these genes were also upregulated in CRC cancer tissues compared with their levels in matched normal tissues." (PMID 35909892, 2022). "INHBA, RPL22L1, CAPZA1, and HMGCS2 showed significant differential levels in dMMR/MSI cancer tissues and were finally selected for further detection." (PMID 35909892, 2022). "These are worthwhile to point out that CST1, CHI3L1, UBD, and INHBA genes were verified by the GEPIA in both COAD and READ cancer types while ASCL2 was verified only in COAD cancer type by the GEPIA." (PMID 35333898, 2022). "In cancer tissues, RPL22L1 and INHBA were significantly upregulated in CRC with positive lymph nodes." (PMID 35909892, 2022). "Our work predicted several candidates as potential biomarkers for distinct stages of GE cancers, including previously identified CST1, INHBA, STMN1, whose expression correlated with cancer recurrence, or resistance to adjuvant therapies or surgery." (PMID 33828156, 2021). "Specifically, a COL11A1/INHBA/THBS2-expressing gene signature was found to be present only after a particular staging threshold, different in each cancer type, was reached." (PMID 34283835, 2021).
cancer (continued). "Our findings provide significant new information on the specific cancers impacted by the genes investigated here, INHA, INHBA, INHBB, ENG and TGFFBR3, and shed light on potential functional dependencies." (PMID 33819300, 2021). "Accumulating evidence indicates that INHBA (Inhibin β-A, a member of the TGF-β superfamily) functions as an oncogene in cancer progression." (PMID 34346300, 2021). "The alterations for the genes varied, with INHBA and TGFBR3 exhibiting higher rates of alterations (0–5.65% and 0.17–3.91% respectively) that also varied by cancer type." (PMID 33819300, 2021). "Since then, many research results were published connecting one of the genes COL11A1, INHBA, THBS2 with poor prognosis, invasiveness, metastasis, or resistance to therapy, in various cancer types." (PMID 34283835, 2021). "Emerging evidence has demonstrated that inhibin subunit beta A (INHBA) is dysregulated and plays a critical role in various cancers." (PMID 34889158, 2021). "Inhibin βA (INHBA), is a member of the transforming growth factor-β (TGF-β) superfamily, that been found to participate in invasion and metastasis in various malignant tumors." (PMID 32293338, 2020). "LIF overexpression enhanced INHBA expression to regulate cancer cell motility, whereas LIF knockdown reduced cell motility and INHBA expression in shLIF transfectants." (PMID 31973037, 2020). "A majority of these genes had been described in different cancers, including FBLN1 or INHBA, but only a few in CRC." (PMID 24516561, 2014). "Inhibin beta A (INHBA) subunits form a homodimer, activin A, which stimulates VEGF gene expression in carcinoma cells and in the v-akt murine thymoma viral oncogene homolog (AKT) pathway." (PMID 21489260, 2011). "INHBA/TGFB1 complex activates SMAD2/3 and improves stem cell characteristics in cancer cells." (PMID 38881758, 2024). "BASP1, FAP, INHBA, and ITGA5 had been reported to be upregulated in several cancers and could regulate neuronal activity, but their relationship with DKK1, nerves, and HNSCC still remains unknown." (PMID 38525111, 2024). "INHBA, HSP90AA1 and EIF2AK2 were overexpressed in cancer tissues and cells of ESCC." (PMID 39006030, 2024). "Consequently, we selected five genes—INHBA, MMP7, PSAT1, SLC7A5, and TGFBI—to evaluate their mRNA expression levels in normal colon tissues compared to their corresponding cancer tissues." (PMID 39628390, 2024). "Although DNA hypomethylation resulting in overexpression of INHBA has been reported in urothelial and gastric carcinomas, the significance of INHBA in HCCs has not yet been clarified." (PMID 36348017, 2023). "In cancer tissues, all subgroups of CXCL14+INHBA+ fibroblasts were highly increased." (PMID 36463319, 2022). "The gene expression profiles revealed that CXCL14+INHBA+ fibroblasts exhibited altered gene expression patterns but did not essentially change their functions in cancer tissues." (PMID 36463319, 2022). "INHBA, MMP1, and SERPINE1 comprised a protein-protein interacting (PPI) network according to STRING network analysis, and these genes were significantly increased in cancer tissues or MSI cancer tissues." (PMID 35909892, 2022). "It is possible that high INHBA expression levels may facilitate the formation of INHBA homodimers, otherwise known as Activin A, leading to the activation of activin receptors such as ACVR1, which has established roles in cancer." (PMID 34642171, 2022). "In line with this hypothesis, it was identified that CAFs exhibiting the “metastasis signature” composed of COL11A1, INHBA (inhibin beta A), THBS2 (thrombospondin 2), originate from adipocytes when the cancer metastasizes to a fat-rich microenvironment." (PMID 33668097, 2021). "INHBA and JAG2 both expressed more in carcinoma tissues than that in adjacent tissues." (PMID 34103052, 2021). "Furthermore, we could show that the knockdown of INHBA attenuated the activity of the ALDH enzyme, a known marker of cancer stem cells." (PMID 38329386, 2024).
cancer (continued). "To better elucidate the induction of EMT by INHBA in PanNENs, we defined 17 upregulated transcription factors in INHBA-overexpressed PanNEN cells and further analyses identified MITF as a regulator of EMT downstream of INHBA, which has been demonstrated in various aggressive cancers." (PMID 38252148, 2024). "Indeed, we found that the mRNA level of INHBA was upregulated in cancer stem cells (spheres or CD133+ population cells) compared with the non-stem cancer cells (adherent or CD133- cells)." (PMID 33537082, 2021). "In addition, we have now identified specific genes (e.g, INHBA and WIF1), which while previously implicated in other cancer types, to our knowledge have not previously been implicated in carcinogenesis of OSCC." (PMID 20174472, 2010). "As expected, the mRNA levels of RPL22L1, INHBA, and CAPZA1 were significantly higher in cancer than in normal tissues; conversely, HMGCS2 was significantly downregulated in cancer." (PMID 35909892, 2022). "In both of these examples, these gene lists are clearly due to the presence of the COL11A1/INHBA/THBS2-expressing CAFs and therefore these are not cancer-type specific subtype signatures." (PMID 34283835, 2021). "The results of qRT-PCR showed that the mRNA expression of INHBA and SPHK1 were significantly increased in cancer than in normal tissues and cells." (PMID 34692520, 2021). "Four genes (SERPINB7, INHBA, GJA1, and NID1) have two isoforms that have significantly different expression between the cancer and non-oncogenic groups." (PMID 23594586, 2013). "Furthermore, stimulation with TGFβ1 upon overexpression of INHBA resulted in activation of the canonical and non-canonical pathways (for OE33 and FLO-1 cancer cells)." (PMID 26447543, 2015).
infection (5 papers, 2019 to 2024). The state of being infected such as from the introduction of a foreign agent such as serum, vaccine, antigenic substance or organism. "The INHBA gene was identified through fine mapping analysis of four a priori identified trypanotolerant associated loci in 360 Ndama cattle under natural infection conditions." (PMID 31699027, 2019). "A similar trend was exhibited by INHBA and BMP2 - genes induced by infection in our bulk RNA-seq results previously shown to be YAP-responsive." (PMID 36923592, 2023). "The transcripts of TNF and RANKL (the TNF family) and of GDF15 and INHBA (the TGF-ß family) were also induced in mice and monkeys upon infection by C. neoformans." (PMID 31329596, 2019).
infectious disease (1 paper, 2019). A disorder directly resulting from the presence and activity of a microbial, viral, or parasitic agent in humans. "The identification of exosomal proteins, such as Serpin A3-7, CCDC88A and INHBA may be harbingers of additional factors that exacerbate infectious disease and metabolic dysfunction, which have long-been associated with reproductive failure." (PMID 31554846, 2019).
metabolic disease (1 paper, 2019). A congenital disorder (due to inherited enzyme abnormality) or acquired (due to failure of a metabolically important organ) disorder resulting from an abnormal metabolic process. "Inhibin or activin β A chain (INHBA) was also unique in exosomes from cows categorized at high-risk of metabolic disease." (PMID 31554846, 2019).
reproductive diseases (1 paper, 2024). "Evidence proposed that the dysregulation of STC1, TIMP3, ITGA2, and INHBA is associated with the development of severe reproductive diseases." (PMID 38730500, 2024).